CCND1 (cyclin D1)
Diseases named in the same sentence as CCND1 in open-access papers (continued):
Sharing a sentence is not in itself a finding about the gene and the disease.
breast cancer (continued). "For example, increased cyclin D1 mRNA and amplification of CCND1 in ER+ breast cancers strongly correlated with increased risk of relapse, local recurrence, metastasis, and death, and ER- patients with cyclin D1 overexpression display shorter overall survival." (PMID 23886499, 2013). "Constitutive CCND1/CDK2 activity conferred resistance to TGF-β induced growth arrest in MMTVD1-K2 driven mouse mammary tumor cells, and CCND1 is a downstream effector of RAS." (PMID 23390492, 2013). "Amplification or overexpression of CCND1 has been shown to play a pivotal role in the development of several human cancers, including parathyroid adenoma, breast cancer, colon cancer, lymphoma, melanoma, and prostate cancer." (PMID 23874806, 2013). "Amplification of the CCND1 gene has been identified in approximately 15 to 20% of human breast cancers, while overexpression of cyclin D1 protein has been demonstrated in 50 to 70%." (PMID 23336272, 2013). "In this study, we found that TGFβ induced mRNA and protein expression of cyclin D1 in breast cancer cells with a highly migratory phenotype." (PMID 23786849, 2013). "It has been reported that the expression levels of cyclin D1 and cyclin E1 are related to the malignant degree of cancers, including glioma, breast cancer, bladder cancer, etc.." (PMID 23383003, 2013). "Cyclin D1 is an oncogene that is over-expressed in about 50% of all breast cancer cases, and its down-regulation is an important target in breast cancer therapy." (PMID 24330704, 2013). "Along with anti-proliferative and growth inhibitory effect, ST induced G0/G1 cell cycle arrest via modulation of cell cycle regulators CDK4, cyclin D1, p21/Cip1and p27/Kip1 breast cancer cells." (PMID 24160369, 2013). "As CCND1 was a critical oncogene for breast cancer, we sought to address its importance in this model." (PMID 24260413, 2013). "Down-regulation of E-cadherin and β-catenin accumulation in the cytoplasm/nucleus has been proposed to promote malignant transformation and progression by triggering cyclin D1 expression in breast cancer." (PMID 23840677, 2013). "Rather, we propose that a dual treatment strategy targeting CCND1/CDK4 and CCND1/CDK2 complexes will be necessary to effectively treat luminal breast cancers arising from elevated CCND1." (PMID 23390492, 2013). "It has been shown previously that in breast cancer cell lines administration of CSF-1 activates cyclin D1, as a consequence of ERK1/2 activation." (PMID 23561040, 2013). "Our study further revealed that TGFβ-induced nuclear cyclin D1 promotes cell migration by altering cell morphology and the formation of invasive subcellular structures in metastatic breast cancer cells." (PMID 23786849, 2013). "We showed a TGFβ-induced nuclear localization of cyclin D1 in these metastatic breast cancer cell lines." (PMID 23786849, 2013). "Previous studies have demonstrated a correlation between Cyclin D1 over-expression and breast cancers." (PMID 23327593, 2013). "In this case, increased expression of PAK1 in breast cancer cells stimulates cyclin D1 promoter activity, increases cyclin D1 mRNA levels, and promotes nuclear accumulation of cyclin D1." (PMID 23950862, 2013). "Orthotopic injection of cyclin D1/p21 null human breast cancer cells in nude mice considerably reduced mammary tumor growth in vivo, compared to animals injected with parental tumor cells." (PMID 23786849, 2013).
breast cancer (continued). "Together, these results demonstrate that cyclin D1 is required for TGFβ-mediated migration in breast cancer cells." (PMID 23786849, 2013). "Luminal breast cancers harboring elevated CCND1 would contain both CCND1/CDK4 and CCND1/CDK2 complexes." (PMID 23390492, 2013). "Overexpression of p21 and cyclin D1 is correlated with poor prognosis and aggressiveness in breast cancer." (PMID 23786849, 2013). "Our results are consistent with previous studies showing similar leptin induction of cyclin D1 expression in human breast cancer, the colon cancer cell line HT-29, and human hepatocarcinoma cells." (PMID 22968658, 2013). "The inhibition of STAT3 by LLL12 also down-regulated the expression of several known STAT3-regulated genes in breast cancer stem-like cells such as Cyclin D1, survivin, Bcl-2, Bcl-XL and an IL-6 regulated gene, Notch1." (PMID 24376586, 2013). "Cyclins and cyclin-dependent kinases (CDK) are frequently dysregulated in cancer, and over-expression of cyclin D1 (CCND1) occurs in approximately 50% of breast cancers." (PMID 23390492, 2013). "Understanding the requirements of human breast epithelial cell transformation and the unique role of constitutive CCND1/CDK2 activity can guide the development of targeted strategies to treat breast cancer." (PMID 23390492, 2013). "Elevated NFkB binding activity has been observed in both primary human breast cancer tissues and breast cancer cell lines, and contributes to the activation of CYCLIN D1, c-MYC, and MUC1." (PMID 24243820, 2013). "Sorafenib, SC-1 and SC-43 induced apoptosis in association with downregulation of p-STAT3 and its downstream proteins cyclin D1 and survivin in a dose-dependent manner in breast cancer cell lines (HCC-1937, MDA-MB-468, MDA-MB-231, MDA-MB-453, SK-BR3, MCF-7)." (PMID 23938089, 2013). "In case of leukemia, prostate and breast cancer, cyclin D1 is released in an amount more than a normal levels and coumarin derivatives have also been found very effective antiproliferative agents by regulating the release of cyclin D1." (PMID 23587363, 2013). "Cyclin D1 has previously been reported to regulate cellular migration in primary bone macrophages, mouse embryo fibroblasts (MEFs), and breast cancer cells." (PMID 23786849, 2013). "In this study, we showed that TGFβ significantly induced cyclin D1 expression in metastatic breast cancer cells." (PMID 23786849, 2013). "We show in this cohort that the expression of two of the studied markers, p16 and cyclin D1, correlates with better prognosis of breast cancer." (PMID 23336272, 2013). "It is well known that cyclin D1 is an estrogen responsive gene that contributes to the estrogen-stimulated proliferation of breast cancer cells." (PMID 24137325, 2013). "While gene amplification is consistently associated with reduced patient survival times and treatment resistance, repeated attempts to clarify the prognostic and predictive impact of the cyclin D1 protein in breast cancer have yielded contrasting results." (PMID 22924091, 2012). "In up to 50% of primary breast cancers the overexpression of cyclin D1 mRNA and protein has been observed." (PMID 23320178, 2012). "Cyclin D1 overexpression is predominantly found in estrogen receptor positive breast cancer, which is a major subtype of human breast cancer." (PMID 23320178, 2012). "A critical role of cyclin D1 in the breast cancer cell proliferation has been proposed by several laboratories and recently documented in the signaling by anterior gradient-2." (PMID 22799881, 2012). "Next, the remaining tumors should be examined for cyclin D1 protein expression in the context of well-defined breast cancer subgroups." (PMID 22924091, 2012). "Nevertheless, the fact remains that tumors associated with ER positivity, specifically those in the luminal breast cancer subgroups, tend to express more cyclin D1 on the mRNA and protein levels than do those that are ER negative." (PMID 22924091, 2012).
breast cancer (continued). "Recently, miR-195 and miR-497 were shown to suppress breast cancer cell proliferation and invasion via targeting Raf-1 and CCND1." (PMID 22723898, 2012). "Prominent examples are genome-wide association studies which led to the identification of novel breast cancer risk factors such as polymorphisms in FGFR2, CCND1, TOX3, MAP3K1, LSP1, CDKN2A, and 2B." (PMID 23226154, 2012). "Down-regulation of cyclin D1 in response to metformin has been shown in several cancer cell lines including breast cancer and prostate cancer cells." (PMID 23151022, 2012). "Clearly, if cyclin D1 is to succeed as a prognostic or treatment predictive biomarker in breast cancer, a stronger selection criterion must be imposed on tumor samples to achieve consistent results." (PMID 22924091, 2012). "To be more precise, we have failed to consistently separate these two very different biological phenomena when determining the relevance of cyclin D1 in a breast cancer setting." (PMID 22924091, 2012). "As expected, the classic known breast cancer amplicons were the most common, including the CCND1 amplicon at 11q13 in 18 tumors, the ERBB2 amplicon at 17q12 in 17 tumors followed by 8p12 and 20q amplicons in 11 tumors." (PMID 23186559, 2012). "In ERα positive breast cancer, coincident cyclin D1 expression in untreated women has been repeatedly presented, although not always, as a positive prognostic factor." (PMID 24575359, 2012). "The abundance of cyclin D1 is rate-limiting in breast cancer cellular proliferation and G1-S phase transition." (PMID 22382486, 2012). "In the present group of male breast cancers, tumors with CCND1 copy number gain tended to have a higher mean mitotic count compared to tumors without CCND1 amplification, a finding which is in line with the encoding protein function." (PMID 22527098, 2012). "Induction of cyclin D1 by pp60v-src is also mediated via the p38/JNK-ATF-2/CREB pathway in human breast cancer cells." (PMID 22404972, 2012). "The expression of cyclin D1, a gene involved in G1 phase cell cycle progression, is induced by E2 in human breast cancer cells." (PMID 22260523, 2012). "Gene amplification of CCND1 is observed in a subgroup of breast cancers with poor prognosis, whereas overexpression of the protein cyclin D1 has been linked to both worse and better clinical outcome." (PMID 22475046, 2012). "In the breast cancer, PPFIA1 is coamplified with CCND1, which is significantly associated with high-grade phenotype but not tumor stage or nodal stage." (PMID 22920630, 2012). "In unsupervised hierarchical clustering a distinctive group of male breast cancer with poor prognosis (p = 0.009; hazard ratio 3.4) was identified, characterized by frequent CCND1, MTDH, CDC6, ADAM9, TRAF4 and MYC copy number gain." (PMID 22527098, 2012). "Cyclin D1 has remained a putative prognostic and predictive biomarker in breast cancer for well over a decade." (PMID 22924091, 2012). "Amplification was observed over cancer genes previously implicated in breast cancer development including ERBB2, CCND1, MYC, MDM2, ZNF217, and ZNF703 and a homozygous deletion involving MAP2K4 was identified." (PMID 22608084, 2012). "A similar study demonstrated that overexpression of cyclin D1 reversed the growth inhibitory effect of tamoxifen in two ER-positive breast cancer cell lines." (PMID 22475046, 2012). "The 34 kDa G1 to S-phase transition marker cyclin D1 represents the best studied cell cycle protein and has been well established as a human oncogene in a breast cancer setting." (PMID 22924091, 2012). "In women, the majority of tamoxifen resistant breast cancers express ERα with co-expression of cyclin D1 with ERα frequently found in cancers resistant to tamoxifen." (PMID 24575359, 2012).
breast cancer (continued). "All of them turned out to be positive (, binomial test), varying between 0.34 for CCND1 in lung cancer cells and for CCND1 in breast cancer cells." (PMID 22347440, 2012). "The rat mammary tumors from auraptene 500 ppm group showed significant reduction in cyclin D1 protein expression." (PMID 23320178, 2012). "Amplification of the cyclin D1 gene (CCND1) occurs in 15 % of primary estrogen receptor (ER) positive breast cancers, while overexpression of the protein is found in 50 % of cases." (PMID 22924091, 2012). "In summary, CCND1 amplification and low nuclear expression of cyclin D1 predicted poor clinical outcome in postmenopausal breast cancer patients treated with either anastrozole or tamoxifen." (PMID 22475046, 2012). "FOXO3A and CCND1 have been demonstrated to be important in both breast cancer and the lapatinib response." (PMID 22709873, 2012). "It has been established that anti-estrogen treatment of MCF7 breast cancer cells induced reduction of c-Myc expression, resulting in cyclin D1 downregulation and eventually cell cycle arrest." (PMID 23351343, 2012). "The oncogenic capabilities of the cell cycle protein cyclin D1 have long been established in a breast cancer setting." (PMID 22924091, 2012). "Overexpression of cyclin D1 is observed in approximately 50% of breast cancers, and cyclin D1 is one of the most commonly overexpressed proteins in this form of cancer." (PMID 22475046, 2012). "EGFR (p = 0.005) and CCND1 (p = 0.041) copy number gain were independent predictors of gender in logistic regression, and these genes were more often gained in male breast cancer." (PMID 22527098, 2012). "Recent genome-wide association studies revealed strong evidence for more than 18 common breast cancer susceptibility alleles including FGFR2, CCND1, TNRC9, MAP3K1, and LSP1." (PMID 23226154, 2012). "Increased levels of messengers cMYC and CCND1 are often observed in different tumour types, such as breast cancer, endometrial cancer, thyroid cancer and ovarian cancer." (PMID 22520842, 2012). "Cyclin D1 expression levels in these mice are comparable to those found in cultured human breast cancer cells." (PMID 24575359, 2012). "We have previously demonstrated that an extract of mushroom G. lucidum, which contains 6% of GLT, suppressed cyclin D1 expression and NF-κB activity in human breast cancer cells." (PMID 23118901, 2012). "Since cyclin D1 protein expression was reduced in mammary tissues of auraptene treated rats, we explored the effect of auraptene on cell cycle in human breast carcinoma cell line MCF-7, which is positive for the estrogen receptor." (PMID 23320178, 2012). "Compared to female breast cancer CCND1 and EGFR were found to be more frequently amplified in male breast cancer, while in females EMSY and CPD were more often involved and more frequent amplifications of TRAF4 and EMSY were found." (PMID 22527098, 2012). "We found that treating MDA-MB-468, MDA-MB-231, and MCF-7 breast cancer cells with these phosphatase inhibitory toxins decreased levels of cyclin D1." (PMID 22069692, 2011). "Our data are in line with previous studies in which breast cancer cell lines expressing ectopic CSF-1R showed increased expression of cyclin D1 as a consequence of ERK1/2 activation upon CSF-1 administration." (PMID 22096574, 2011). "We also demonstrate that c-Jun, cyclin D1 and c-Myc, known for their involvement in cell proliferation, are downstream CSF-1R in breast cancer cells." (PMID 22096574, 2011). "In fact aberrant over-expression of cyclin D1 occurs in 70-100% of breast tumor cell lines and most breast cancers and seems to be required for neu and Ras-induced mammary epithelial transformation." (PMID 21272329, 2011).
breast cancer (continued). "It has previously been shown that silencing cyclin D1 increases the migratory capacity of MDA-MB-231 breast cancer cells with concomitant increase in 'inhibitor of differentiation 1' (ID1) gene expression." (PMID 21955753, 2011). "For example, a great majority of small cell lung cancers, breast cancers, glioblastomas and mantle cell lymphomas have over-expression of cyclin D1 or its catalytic partner, Cdk4." (PMID 21272329, 2011). "The genetic variants within ER cofactors have not been systematically investigated in term of association with breast cancer risk, although some coding variants within individual genes, such as NCOA3 and CCND1, have been investigated." (PMID 21269472, 2011). "Other over-expressed members of the cluster, such as miR-17-5p/miR-20, have been linked to the regulation of cell proliferation through a Cyclin D1 regulatory feedback loop and through the inhibition of AIB1 translation in breast cancer." (PMID 21364938, 2011). "Those CRC with strong cyclin-D1 expression showed positive correlation with nEGFR, as also found in breast cancer." (PMID 22050898, 2011). "We found ERK1/2, c-Jun, cyclin D1 and c-Myc, known for their involvement in cell proliferation, to be downstream CSF-1R in breast cancer cells." (PMID 22096574, 2011). "Calyculin A induces T286 phosphorylation and proteosome-mediated degradation of cyclin D1 in human breast cancer MDA-MB-468 and MDA-MB-231 cells." (PMID 22069692, 2011). "In this study, we demonstrate that silencing Id1 prevents the cyclin D1 mediated increase in MDA-MB-231 breast cancer cell migration." (PMID 21955753, 2011). "Cyclin D1 regulates the G1 to S progression of the cell cycle and is over expressed at the protein level in several cancers including ~50% of breast cancers, as seen by immunohistochemistry." (PMID 22069692, 2011). "Cyclin D1 is a key regulator of the cell cycle that is over expressed in more than half of breast cancer patients." (PMID 22069692, 2011). "Knockdown of USP2 in HCT116 colorectal cancer, MCF-7 breast cancer, and PC-3 prostate cancer cells destabilized cyclin D1 and reduced cell proliferation." (PMID 22069692, 2011). "Given the role of Id1 in cell invasion and metastasis, it represents a strong candidate for driving breast cancer cell migration following cyclin D1 silencing." (PMID 21955753, 2011). "Here we analyzed the effect of 4-HPR in inhibiting the growth of several RT, glioma, and breast cancer cell lines and tested their effect on cell cycle, apoptosis and Cyclin D1 expression." (PMID 21951911, 2011). "Previous studies have shown that high expression of cyclin D1 and Jagged-1 correlate with poor prognosis in breast cancer." (PMID 22113133, 2011). "It has been demonstrated that employment of PGA2 induced AUF1 expression and resulted in degradation of cyclin D1 mRNA in non small cell lung cancer (H1299) and breast carcinoma (MCF-7) cells." (PMID 21835052, 2011). "There is mounting evidence that cyclin D1 plays a critical role in breast cancer cell cycle control." (PMID 20863366, 2010). "It has been shown, in breast cancer cells, that C/EBPβ is a constitutive repressor of cyclin D1 target genes and that cyclin D1 acts by antagonizing this repressor function." (PMID 20459741, 2010). "To gain a deeper understanding of the effects of BEX2 expression in c-Jun-mediated cellular functions we investigated the effect of BEX2 on cyclin D1 which is a known c-Jun target of obvious importance in breast cancer." (PMID 20482821, 2010). "The induction of cyclin D1 in breast cancer cells shortens the G1 phase and increases the number of cells that progress through the G1 phase, resulting in an increased proliferation." (PMID 20863366, 2010). "To begin to elucidate the mechanism of Sox2-induced neoplasia, we stained sections of tumors from Scgb1a1-CreER; homozygous Rosa26R-Sox2-IRES-GFP lungs for Cyclin D1, a target of Sox2 in breast cancer cell lines." (PMID 20548776, 2010).